TNF (tumor necrosis factor)
Diseases named in the same sentence as TNF in open-access papers (continued):
Sharing a sentence is not in itself a finding about the gene and the disease.
glioma (continued). "Thrombin was previously shown to activate C6 glioma cells in vitro, resulting in the expression of TNF-α." (PMID 36142385, 2022). "The IL-1β, IL-18, TNF-α, and other cytokines in microglia are released and act on glioma to promote tumor cell proliferation." (PMID 36713560, 2022). "Previously, RORα overexpression abrogated glioma tumorigenesis through reducing TNF-α-mediated NF-κB signaling." (PMID 35440077, 2022). "For the upregulated genes in the combination treated tissue compared with the Ad-SGE-REIC-treated U87ΔEGFR glioma tissue, 12 significantly enriched pathways were identified, including the TNF-alpha NF-kB Signaling Pathway and Delta-Notch Signaling Pathway." (PMID 36006934, 2022). "In summary, our results indicate that the TNF-α/TNFR1/ANXA1 axis regulates the proliferation of glioma cells and that ANXA1 plays a regulatory role in the inflammatory microenvironment." (PMID 35415239, 2022). "TNF-α strengthens glioma proliferation, migration, and therapy resistance by activating NF-κB signaling." (PMID 36091778, 2022). "The TNF-α protein level was elevated by 3.18- and 8.75-fold in the glioma TME after treatment with SR717@RGE-HFn NPs compared to the free SR717 or PBS groups, respectively." (PMID 35386310, 2022). "In summary, our findings indicated that the TGF-β/CLDN4/TNF-α/NF-κB signal axis plays a key role in the biological progression of glioma." (PMID 35418179, 2022). "Our experiments identified that expression of TNFR1 and ANXA1 is altered in glioma cells stimulated with TNF-α." (PMID 35415239, 2022). "In summary, our study elaborates on the possible mechanism of ANXA1 in the inflammatory microenvironment of glioma cells upon TNF-α stimulation and the role of ANXA1 in glioma cell proliferation." (PMID 35415239, 2022). "Both the TGF-beta pathway and the TNF-alpha signaling pathway through NF-kB are important molecular processes for glioma growth and invasion." (PMID 36231068, 2022). "The real-time reverse transcription (RT)-polymerase chain reaction (PCR) study showed that complex 4c inhibited the TNF-α-induced NF-κB phosphorylation in glioma cells." (PMID 35873312, 2022). "The enhanced production of TNF-α in the glioma TME suggested that SR717@RGE-HFn NPs stimulated a profound anti-glioma immune response." (PMID 35386310, 2022). "HT alone reduced the invasion of C6 glioma cells by stimulating TNF-α signaling to activate apoptosis, enhancing p38 MAPK expression, and inhibiting the NF-κB pathway." (PMID 35453310, 2022). "In human glioma cell lines and glioma stem cells, RORα overexpression inhibits proliferation and tumorigenesis by inhibiting the TNF-α-mediated NFκB signaling pathway." (PMID 35605663, 2022). "TNF-α has been shown to induce IL-6 release from C6 glioma cells by modulating NFκB transcriptional activity." (PMID 35992852, 2022). "The purpose of this study was to explore the regulatory mechanism of Annexin A1 (ANXA1) in glioma cells in the inflammatory microenvironment induced by tumour necrosis factor α (TNF-α) and its effects on glioma cell proliferation." (PMID 35415239, 2022). "Other evidence reveals that the activation of phosphorylated p38MAPK expression mediates TNF‐α‐induced apoptosis in glioma cells." (PMID 35986371, 2022). "Genetically modified MSCs expressing an apoptosis-inducing ligand associated with tumor necrosis factor (TNF) (TRAIL) demonstrated targeted delivery and local production of TRAIL at the glioma tumor site." (PMID 36109754, 2022). "Our previous studies also demonstrated that RORA inhibits the proliferation and tumorigenesis of glioma via inhibiting the TNF-α-mediated NF-kB signaling pathway." (PMID 35945192, 2022). "DRB reduced glioma cell viability in vitro, inhibited TNFα (tumour necrosis factor α)-mediated NF-κB activation, and sensitized cells to TNFα-induced apoptosis." (PMID 35214064, 2022).
glioma (continued). "Changes in tumour necrosis factor receptor 1 (TNFR1) and ANXA1 expression in glioma cells stimulated with TNF-α were revealed through western blot analysis and immunofluorescence staining." (PMID 35415239, 2022). "All these results indicate that ANXA1 contributes to glioma cell proliferation upon TNF-α stimulation." (PMID 35415239, 2022). "Considering that chemerin and TNF-α have been shown to activate NF-κB signaling, which is an important pathway that regulates the mesenchymal features of glioma, we suggest an important role for NF-κB signaling in the chemerin/CMKLR1 axis in GBM." (PMID 35459783, 2022). "Real-time reverse transcription (RT)-polymerase chain reaction (PCR) studies revealed that complex 4c inhibited the TNF-α-induced NF-κB phosphorylation in glioma cells." (PMID 35873312, 2022). "CK2 siRNA reduced glioma cell viability, inhibited TNFα-mediated NF-κB activation, and sensitized cells to TNFα-induced apoptosis." (PMID 35214064, 2022). "This renounces the antitumor activity and contributes to glioma invasion, releasing multiple cytokines, i.e., IL-1β, IL-6, IL-8, IL-10, and TNF-α." (PMID 35454935, 2022). "As shown by the bean plot, 7 genes (RIPK1, RIPK3, FAS, FADD, FASLG, TLR3, and TNF) were upregulated in the glioma tissues with p <0.001." (PMID 35719998, 2022). "Levels of the Ifnb1, Cxcl9, Cxcl10 and TNF-α mRNAs in glioma tissues from different treatment groups were determined using qRT-PCR to evaluate the activation of STING signaling." (PMID 35386310, 2022). "TNF-α is one of the major regulators of inflammation and is strongly correlated with progression and clinical aggressiveness in glioma." (PMID 35734424, 2022). "TNF and the associated receptor superfamily are important to the development of glioblastoma, and upregulation of TNF-α is influential to the progression of glioblastoma in U373 glioma cells." (PMID 35368876, 2022). "We next examined the therapeutic potential of targeting TNFα in the established syngeneic glioma mouse model, GL261." (PMID 33853689, 2021). "According to this map, AKT, ERK, and TNF are involved in three signaling pathways and play a pro-proliferation role in glioma." (PMID 34873410, 2021). "More importantly, AKT1, JUN, MAPKs, and TNF contribute to resistance to chemotherapy and radiotherapy, one of the greatest barriers in the treatment of glioma." (PMID 34873410, 2021). "The contribution of inflammation in glioma progression involves the interaction of multiple pathways such as oxidative stress, interleukin, tumor necrosis factor-α (TNF-α), and pro-inflammatory transcription factors (NF-κB, STAT3)." (PMID 34408772, 2021). "In glioma, S100A4 expression is affected by DNA methylation, β-linked proteins, and extracellular factors including epidermal growth factor and tumor necrosis factor alpha (TNF-α)." (PMID 34148033, 2021). "Previous studies of glioma sphere cultures indicated that TNF-α promotes mouse embryonic stem cell differentiation accompanied by increased resistance to radiotherapy in an NF-κB-dependent manner." (PMID 34603399, 2021). "Taken together, these data demonstrate that inhibition of TNFα reduces EC activation and prolongs survival of mouse glioma models and provides support for TNFα serving as a novel therapeutic target in GBM." (PMID 33853689, 2021). "We determined that SLC39A7 promotes the malignant behaviors of glioma by activating the TNF-α-mediated NF-κB signaling pathway." (PMID 34149917, 2021). "Typically, postoperative inflammation occurs at the glioma site, and inflammatory cytokines [interleukin-8 (IL-8) and tumor necrosis factor α (TNF-α)] at the inflammation site activate NEs and induce their migration to the inflammatory site." (PMID 34142930, 2021). "GLP has been shown to prevent glioma growth in glioma-bearing rats by increasing the concentration of serum interleukin-2, tumor necrosis factor-α, and interferon-γ, as well as enhance the cytotoxic activity of natural killer cells and T cells." (PMID 34069721, 2021).
glioma (continued). "Using bioinformatics analysis and in vivo and in vitro experiments, we found that SLC39A7 promotes glioma proliferation, invasion, migration and tumorigenesis via the TNFα-mediated NF-κB signaling pathway." (PMID 34149917, 2021). "Here we have shown that glioma cells induce macrophages to secrete TNFα which act on nearby ECs to upregulate genes involved in EC activation." (PMID 33853689, 2021). "Contemporarily, TNF-α appears to play a fundamental role enabling glioma cells to escape from immune response allowing the appearance of an aggressive growth phenotype in the inflammatory TME." (PMID 33806300, 2021). "Autocrine IFN-β signaling has previously been described, for example in the monocytic leukemic cell line THP-1 after LPS stimulation, in dendritic cells after TLR activation, in glioma cells, and in human foreskin fibroblasts stimulated with TNF." (PMID 33770100, 2021). "TNFα mediated necroptosis is one type of necroptosis cell death in many diseases, such as glioma cells 37 and alveolar epithelial cells." (PMID 34131409, 2021). "By target harvesting, six core genes including AKT1, JUN, ALB, MAPK3, MAPK1, and TNF were screened from a total of 205 targets of luteolin against the glioma network." (PMID 34873410, 2021). "Wogonin also inhibits the progression of gliomas by downregulating the secretion of the inflammatory cytokines TNF-α, IL-6, and IL-1β." (PMID 33897434, 2021). "An in vitro study in murine microglial BV2 cells showed microglial cell activation by conditioned medium from glioma cells via upregulating mRNA expression of inducible nitric oxide synthase (iNOS), interleukin (IL)-1β, IL-6, TNF-α, and COX-2." (PMID 34439380, 2021). "TLR-4 activation in human glioma U251 cells stimulated the production of cytokines (IL-1β, IL-6, IL-8, and TNFα) and increased the expression of stem cell markers such as CD133 and CD34." (PMID 34439380, 2021). "On the other hand, LPS/IFN-γ-stimulated MG can trigger autophagy-dependent death in glioma cells that are resistant to death ligands, like TNF α and TRAIL." (PMID 34671362, 2021). "To investigate the impact of the increased levels of the TNF-α expression on EC activation in GL261 syngeneic glioma mouse model, we performed double IHC staining with CD31 and VCAM1 antibodies." (PMID 33853689, 2021). "For example, the mesenchymal subtype of glioblastoma is characterized by increased levels of NF-κB signaling components and moreover, glioma sphere cultures of the proneural subtype can transform to a mesenchymal state under TNF-α-mediated NF-κB activation." (PMID 34359668, 2021). "Thalidomide reduced inflammatory stimulation, including the production of TNF indirectly, and interfered with the transcriptional regulation of NF‐κB in ECs directly for the simultaneous inhibition of glioma angiogenesis." (PMID 33300633, 2021). "Glioma-derived pro-inflammatory factors, IL-1β, IL-6, TNF-α, and COX-2, were found to accelerate p38 MAPK phosphorylation." (PMID 34439380, 2021). "Activation of NFκB in glioma stem-cell cultures by tumor necrosis factor (TNF) treatment resulted in radiation resistance that can be reversed by blocking NFκB." (PMID 32506371, 2020). "NK cells, by secreting tumor necrosis factor (TNF) and interferon (IFN), kill susceptible target cellsthereby exerting the cytolytic activity and improving the prognosis of patients with glioma." (PMID 33292262, 2020). "This was observed via their cytolytic actions as well as the production of IFN-γ and TNF-α in the presence of IL13Rα2-positive glioma cells." (PMID 33204365, 2020). "Taking these two assays into consideration, it was concluded that TNF-α/IL-6/sIL-6R treatment decreased the tumorigenicity of the C6 glioma cell line." (PMID 33227992, 2020). "This study aimed to investigate the effects and mechanisms of emodin-induced necroptosis in the glioma cell line U251 by targeting the TNF-α/RIP1/RIP3 signaling pathway." (PMID 30924024, 2020).
glioma (continued). "In consideration of this possibility, we treated TNIP1‐interfered glioma cells with the same concentration of TNF‐α and same time course." (PMID 31691497, 2020). "Treatment with IFNγ and TNFα resulted in iNOS expression in glioma cells, which was mediated by p38 MAPK." (PMID 32467752, 2020). "Subsequently, we further confirmed the expression of differentiation markers in TNF-α/IL-6/sIL-6R treated glioma cells." (PMID 33227992, 2020). "The results showed that, compared to control cells, TNF-α/IL-6/sIL-6R treated glioma cells formed more gap junctions with nearby cells." (PMID 33227992, 2020). "Next, we studied possible causes of mTNFα expression impairment ultimately leading to a selective defect in TNFα-mediated cytotoxic function of IFN-DCs from patients with high-grade gliomas against autologous tumor cells." (PMID 32326230, 2020). "In TNF-α/IL-6/sIL-6R treated glioma cells, STAT3 can be phosphorylated (p-STAT3) as a transcription factor to participate in IL-6 signaling." (PMID 33227992, 2020). "This study reports TGFβ1 stimulates beta‐site APP‐cleaving enzyme 2 (BACE2) expression through Smad‐dependent signalling, which modulates TNF‐α‐induced NF‐κB activity through the PP1A/IKK pathway to promote tumorigenesis in glioma cells." (PMID 31856384, 2020). "NO concentration was measured on the BMVECs with the same inflammatory stimuli (100 ng/ml TNF + 5 μg/ml LPS) as was used for the glioma cells." (PMID 33585405, 2020). "CXCL16 is highly expressed in human gliomas, where both mRNA and protein are upregulated by TNFα and IFNγ." (PMID 32456359, 2020). "Our previous studies showed that IFN-DCs from patients with high-grade gliomas (glioblastoma multiforme) in contrast to DCs derived from patients with low-grade gliomas are characterized by impaired TNFα/TNF-R-dependent cytotoxicity." (PMID 32326230, 2020). "Liberated IKK phosphorylated and degraded IκB, with the free NF‐κB then phosphorylated by TNF‐α signalling and translocated into the glioma cell nuclei." (PMID 31691497, 2020). "Down‐regulation of TNIP1 decreased glioma cell proliferation, in which the TNF‐α/NF‐κB signalling pathway was involved." (PMID 31691497, 2020). "Glioma cell proliferation was activated with TNF‐α treatment and showed extreme sensitivity to the TNF receptor antagonist." (PMID 31691497, 2020). "We examined the expression of the Il-6 gene in a tumorigenic C6 glioma cell line treated with IL-6, IL-6/sIL-6R, and TNF-α/IL-6/sIL-6R." (PMID 33227992, 2020). "Further immunoblotting revealed that TNF‐α promoted the phosphorylation and degradation of IκB‐α in glioma cells in a time‐dependent manner, with NF‐κB subunit P65 increasingly expressed and phosphorylated in the same manner (left pane)." (PMID 31691497, 2020). "Our results indicate that increased circulating IL‐6, IL‐8, IL‐17, TNF‐α, TGF‐β, and CRP levels are significantly associated with increased glioma risk." (PMID 31599129, 2019). "We observed significantly higher TNF-α level in the glioma and meningioma group in comparison to the control (P=0.009, p=0.04)." (PMID 31653130, 2019). "TNF-α and IL-1β expressions were significantly higher in the meningioma and glioma group in comparison to control group." (PMID 31653130, 2019). "Our meta‐analysis indicates that increased circulating IL‐6, IL‐8, IL‐17, TNF‐α, TGF‐β, and CRP levels are significantly associated with increased glioma risk." (PMID 31599129, 2019). "We evaluated the therapeutic efficacy of SM on Glioma stem-like cells (GSCs) and showed that this family of compounds stimulates an adaptive response triggered by TNFα." (PMID 30854231, 2019). "The results showed that increased circulating IL‐6, IL‐8, IL‐17, TNF‐α, TGF‐β, and CRP levels before treatment are significantly associated with glioma risk." (PMID 31599129, 2019). "Altogether, these data suggest a role for TNF-α as a critical factor for macrophage-induced glioma cell death after plasma treatment." (PMID 31216715, 2019).
glioma (continued). "Other studies also show that HIV-1 Tat can induce the secretion of TNFα and IL1β from U87 glioma cells." (PMID 30972014, 2019). "As TNF receptors were found to mediate mitogenic effects in many cell types, it was proposed that the reported proliferative effects of TNF-α on astrocytes and C6 glioma cells were mediated by these receptors." (PMID 30442087, 2018). "In our present study, activation of the TLR4 signaling pathway promoted the production of IL-1β, IL-6, IL-10, MCP-1, MIP-1α, and TNF-α in glioma CD133+ CSCs." (PMID 28881826, 2017). "Abnormally expressed cytokines such as interleukins (ILs), colony-stimulating factors, interferons (IFNs), tumor necrosis factor (TNF), transforming growth factor (TGF)-β, and other chemokines have been implicated in glioma progression." (PMID 28389653, 2017). "ZEB1 is associated with malignancy in glioma and analysis of GBM patient specimens demonstrated that proinflammatory cytokines, such as CXCL12, IGFBP2, IL-1ß, TNF-a and MIF, correlate significantly with ZEB1 expression in tumor specimens." (PMID 28445977, 2017). "Analysis of proinflammatory cytokines showed an increase in TNF-α expression in the MC co-cultured glioma cells." (PMID 28445977, 2017). "The real-time qPCR analysis further demonstrated a dramatic increase in TNFα mRNA levels 18 h after treatment with CBD alone in both glioma lines." (PMID 29088769, 2017). "And RCAN1 overexpression exacerbated the glioma cell apoptosis after TNFα treatment (p < 0.005, lane 3 versus lane 4)." (PMID 28061453, 2017). "In an ischemia-reperfusion model, fucoidan from Laminaria japonica reduced the levels of TNF-α, while, in C6 glioma cells treated with TNFα, fucoidan from Fucus vesiculosus has been shown to suppress the expression of iNOS." (PMID 26848666, 2016). "LPS induced ROS in U-87 human glioma cells which allevated pro-inflammatory cytokines (TNF-α, IL-6 and IL-1β)." (PMID 27435304, 2016). "Consistent with its immunosuppressive actions elsewhere in the body, glioma-associated IL-10 down-regulates MHC class II expression on monocytes and inhibits IFN-γ and TNF-α production by immune cells." (PMID 26217588, 2015). "In contrast to other cancer types, TNFα suppresses CHI3L1 expression in glioma cell lines in a NF-κB-dependent manner." (PMID 26425658, 2015). "As a 5-HT2A agonist, DOI was reported to block IL-1β and TNFα release by human PBMCs as well as to inhibit LPS or TNFα-stimulated inducible nitric oxide synthase (iNOS) activity in C6 glioma cells." (PMID 26236313, 2015). "We do not, however, find any evidence for induction of IL13Rα2 through TNF/IL-4 or TNF/IL-13 cytokine regimens on glioma cell lines, either established (T98 or U251T) and/or low-passage primary lines (PBT003-4, PBT008, PBT017-4)." (PMID 24787244, 2014). "At low TNF-α concentration glioma cells have a higher survival rate, while overexpression of TNF-α induces neuronal cell death." (PMID 25182732, 2014). "TNF-α has been recently demonstrated to induce IL-6 expression via STAT3 pathway in C6 glioma cells." (PMID 25275372, 2014). "This normal microglia produced NO in turn stimulated co-cultured glioma cells' migration and their synthesis of tumor necrosis factor-alpha (TNF-alpha) and macrophage chemotactic protein-1 (synonymous with CCL2, MCP-1)." (PMID 25211298, 2014). "In contrast, TNF-α promotes mesenchymal transformation of a proneural glioma stem cell line and increase in YKL-40 and CD44 expression through activation of NF-κB." (PMID 24809021, 2014). "LPS also stimulated microglia to produce TNF-α in vitro, but glioma cells both through paracrine and direct cell-contact mechanisms, inhibited this effect." (PMID 25411122, 2014). "Further, B-D13-PE target antigen was up-regulated on glioma cell lines under a variety of cytokine conditions including TNF alone." (PMID 24787244, 2014). "TNF-α is present in glioma tumors and is thought to be mainly secreted by endogenous microglia or tumor-associated macrophages." (PMID 24244348, 2013).